INS (insulin)
Diseases named in the same sentence as INS in open-access papers (continued):
Sharing a sentence is not in itself a finding about the gene and the disease.
Obesity (continued). "Only one study investigated the response to both insulin and a control substance in groups affected by overweight/obesity and groups of a lean/healthy weight." (PMID 39595054, 2024). "The primary keywords during this period included “fatty acid,” “insulin resistance,” “obesity,” “gene expression,” “hepatocyte,” “apoptosis,” and “free fatty acid,” among others." (PMID 38533910, 2024). "The pancreas’ ability to self-regulate in response to increasing insulin demand is reflected in β-cell proliferation and increased β-cell mass during pregnancy and obesity." (PMID 39045459, 2024). "As obesity impacts glucose metabolism and insulin action, we next analysed the capacity of the mice to break down glucose by performing a glucose tolerance test (GTT) on mice fed with ND or HFD for 20 weeks." (PMID 38533529, 2024). "The occurrence of GDM in our study group is mainly due to overweight and obesity and the subsequently increased insulin resistance and β-cell dysfunction induced by these conditions." (PMID 39064123, 2024). "Pediatric patients with overweight or obesity often exhibit hyperinsulinemia and demonstrate around a 40% reduction in insulin-stimulated glucose uptake compared to children with normal weight." (PMID 39337980, 2024). "In obesity, hypertrophic adipocytes become resistant to the antilipolytic effect of insulin and reduce the capacity to accumulate lipids." (PMID 39683663, 2024). "As a result, the decreased insulin’s ability to down-regulate adipocyte lipolysis in pregnant women with obesity leads to an increase in FFA delivery to the liver and VLDL synthesis in the liver." (PMID 39083072, 2024). "The objective of this study was to assess the prevalence of impaired glucose regulation (IGR) in a large cohort of children and adolescents with obesity and to characterize insulin sensitivity and insulin secretion." (PMID 38550917, 2024). "IR is a metabolic disorder that is often accompanied by obesity, high blood sugar levels, elevated insulin levels, and disturbances in lipid metabolism." (PMID 39180548, 2024). "They reveal how obesity-driven molecular changes, like increased estrogen and insulin levels, contribute to BC via specific signaling pathways." (PMID 38699635, 2024). "It has been suggested that white adipose tissue (WAT) stores energy as triacylglycerols, and in obesity, it becomes dysfunctional and promotes a pro-inflammatory, hyperlipidemic, and insulin-resistant environment." (PMID 38921471, 2024). "To deeply investigate the metabolic adaptive response to obesity we evaluated the glucose tolerance, insulin sensitivity, and insulinemia after 20 weeks on the HDF feeding program." (PMID 39741884, 2024). "Glucagon-like peptide 1 (GLP-1) agonist (e.g., Semaglutide) decreases steatosis, obesity, insulin sensitivity, and CV risks." (PMID 39411175, 2024). "UBNS palmitate release rates (μmol/min) were significantly (at least P < 0.001) sequentially suppressed by low- and high-dose insulin in both volunteers with obesity and lean volunteers." (PMID 38602778, 2024). "In obesity, adipocyte insulin sensitivity (half maximum effective hormone concentration) and maximal antilipolytic effect were tenfold and 10% lower, respectively, in men than women (p = 0.005 or less)." (PMID 38491191, 2024). "This has been demonstrated by studies using rodents, which show that suppression of obesity through the removal of visceral adipose tissue results in improved insulin action and prolongs lifespan." (PMID 38672227, 2024). "Magnesium (Mg), manganese (Mn), and chromium (Cr) emerge as crucial elements intricately involved in the molecular modulation of vital physiological processes, notably obesity, insulin sensitivity, liver insulin resistance, and systemic inflammation." (PMID 38689728, 2024). "Forty-one proteins were associated with obesity (FDR < 0.05), 29 of which had strong associations with insulin-related traits and lipid profiles (FDR < 0.05)." (PMID 38548792, 2024).
Obesity (continued). "Vitamin D exerts multifaceted regulation within the human body, impacting intricate mechanisms such as insulin resistance, immune response, and inflammatory pathways, which are crucial in studying the relationship between vitamin D and obesity." (PMID 39092232, 2024). "The reductions in HbA1c and FPG observed in obese individuals following taurine supplementation further supports its positive effect on insulin sensitivity in obesity." (PMID 39796489, 2024). "Obesity-related factors such as chronic inflammation, insulin resistance, and increased appetite-regulating hormones, such as ghrelin, contribute to disrupted sleep patterns, including obstructive sleep apnoea (OSA)." (PMID 39519418, 2024). "Obesity-induced neuroinflammation was first described in the hypothalamus, evidenced by the upregulation of JNK and NF-kB signaling and a reduced insulin and leptin profile caused by exposure to a high fat diet (HFD)." (PMID 38598021, 2024). "The improvement in insulin action occurred in parallel with the higher activation of AMPK in the skeletal muscle of individuals with severe obesity." (PMID 38324260, 2024). "Several factors can influence the production and secretion of omentin-1, including obesity, insulin sensitivity, inflammation, genetic factors, and hormones, such as adiponectin and insulin." (PMID 38397886, 2024). "In the whole population, BMD (femoral neck) was explained by MetS (p < 0.0001, α = 0.99, ANOVA) with the confounding factors BMI, obesity, or WC, as well as glycemia, insulin levels, and HOMA-IR." (PMID 38731059, 2024). "Subsequently, we examined the effect of succinic acid on HFD-induced obesity by weighing mice and adipose tissue, conducting insulin sensitivity tests, and glucose tolerance tests." (PMID 39599615, 2024). "Obesity affects the genes involved in energy balance, fat storage, lipid metabolism, and insulin signaling, suggesting that the environment during sperm development is crucial for long-term health outcomes in offspring." (PMID 39770898, 2024). "Considering the prevalence of obesity with PCOS and its association with HTN, maintaining a balanced diet and regular exercise has proven to increase metabolism, improve insulin sensitivity, and help lose weight safely, all contributing to reducing BP." (PMID 39507182, 2024). "Studies have indicated that PreAs from individuals with obesity and T2D display compromised insulin signaling." (PMID 38812572, 2024). "Several metabolites derived from intestinal microbiota (IM), such as branched-chain amino acids and their metabolites, tryptophan and its metabolites, SCFAs, etc., are involved in the occurrence and development of obesity by affecting insulin resistance." (PMID 39200098, 2024). "HFD rats had increased colonic acetic acid incorporation, and chronic acetic acid administration induced obesity-related MetS complications and led to parasympathetic β-cell stimulatory insulin secretion." (PMID 38474087, 2024). "Multiple rodent studies have demonstrated that transplanted BAT improves glucose tolerance, insulin sensitivity and reduces obesity." (PMID 38339160, 2024). "Several studies in the following years demonstrated that targeting TNF by specific monoclonal antibodies improved insulin sensitivity and improved hepatic steatosis, which is frequently observed in obesity and obese mice." (PMID 38672492, 2024). "Second, treating obesity is complicated by intensive insulin therapy, the standard of care for T1D, which paradoxically causes weight gain, creating a challenging dilemma for achieving weight management goals." (PMID 38092958, 2024). "A study in normal-weight men found that insulin infusion-induced hyperinsulinemia, of the magnitude observed in insulin resistant states such as obesity, produced IR." (PMID 39012663, 2024). "Obesity can impair insulin signaling that is crucial for hepatic, pancreatic, and neuronal function." (PMID 39897964, 2024).
Obesity (continued). "The present study demonstrates the insulin-sensitizing, glucose-regulating, anti-obesity, and anti-hyperlipidemic properties of Furocyst in women with PCOS." (PMID 39734992, 2024). "This study aimed to investigate alterations in insulin sensitivity among newborns born to mothers with obesity." (PMID 38469369, 2024). "RSV has also been suggested as a potential anti-obesity compound, mimicking the effects of energy restriction and leading to reduced body fat and improved insulin sensitivity." (PMID 39598748, 2024). "Reducing circulating insulin with metformin or pioglitazone prevents obesity-related airway hyperresponsiveness in rats." (PMID 39316677, 2024). "In conclusion, adhering to plant-based diets for ≥14 d improved HOMA-IR and fasting insulin in people with overweight/obesity." (PMID 38999858, 2024). "Identifying these key metabolic pathways suggests potential therapeutic targets for improving insulin sensitivity and overall metabolic health in T2D and obesity." (PMID 39195507, 2024). "Improved effectiveness in managing obesity, insulin sensitivity, and gut dysbiosis in individuals with MetS." (PMID 39429422, 2024). "Insulin-stimulated glycogen synthesis was reduced in myotubes from women with severe obesity compared with lean donors (10.9 ± 0.5 vs. 9.4 ± 0.2 nmol/min/mg, for lean vs. severely obese, respectively, P < 0.05) with and without resveratrol treatment." (PMID 38324260, 2024). "The findings of this study suggest that supplementation with 30 g MPC per day for 8 weeks in women with obesity following a weight-loss diet resulted in reductions in BMI, WC, fat mass, FBS, insulin, LDL-C, and leptin, and an increase in HDL-C and adiponectin." (PMID 38831442, 2024). "Meg3 levels have previously been shown to be low in obesity, and our results concur with the earlier finding that showed the role of Meg3 in glucose homeostasis and insulin signaling." (PMID 39596898, 2024). "Flavonoids in buckwheat also enhance insulin sensitivity, lower blood glucose levels, and regulate lipid metabolism, thereby mitigating obesity." (PMID 39767010, 2024). "Crucially, METS-IR integrates aspects of obesity and metabolic syndrome and avoids dependence on fasting insulin levels." (PMID 38711979, 2024). "Obesity leads to changes in serum lipids, increasing insulin resistance and promoting systemic inflammation." (PMID 38999820, 2024). "This process enlarges adipocytes and increases lipid content, suggesting a potential role of insulin in driving obesity." (PMID 38721091, 2024). "Obesity decreases the production of adiponectin, a hormone that has anti-inflammatory and insulin-sensitizing characteristics." (PMID 39630623, 2024). "Pharmacological depletion of insulin prevented the development of obesity-induced airway hyperresponsiveness." (PMID 39316677, 2024). "Expression of the Fkbp5 gene is associated with reduced glucose uptake and acts as a negative regulator of the protein kinase B (PKB) pathway, leading to impaired insulin signaling, which is expected to prevent high-fat diet-induced obesity." (PMID 39409181, 2024). "It is an anti-diabetic drug that works by increasing insulin sensitivity with the expense of inducing adipogenesis and weight gain, thus supporting the proposed mechanism of obesogens contributing to obesity." (PMID 38790597, 2024). "For instance, research on obese women has indicated that moderate obesity correlates with heightened proteolysis and impaired anti-proteolytic effects of insulin." (PMID 39007094, 2024). "High DII stimulates insulin secretion in various ways, such as inhibiting fat oxidation, facilitating carbohydrate oxidation, increasing fat storage, and promoting obesity." (PMID 38268038, 2024). "New anti-diabetic drug classes (SGLT2 inhibitors, GLP-1 agonists), improved insulin formulations, and novel treatments for obesity and kidney protection (e.g., bardoxolone) have expanded the pharmacopeia." (PMID 38686257, 2024).
Obesity (continued). "In obesity, circulating saturated fatty acids (SFAs) and inflammatory cytokines interfere with skeletal muscle insulin signaling, leading to whole body insulin resistance." (PMID 38999834, 2024). "Increased basal [Ca2+]i dynamics and insulin secretion have previously been described in vivo in a model of diet-induced obesity as an adaptive compensatory mechanism in prediabetes." (PMID 38814444, 2024). "This action prevents the accumulation of glycerol within the cells, which occurs only in pathophysiological conditions and which negatively affects insulin sensitivity, thereby contributing to the development of obesity." (PMID 39408213, 2024). "In this respect, D-mannose is obviously different from glucose and initiates a complex of ACSS2 and PPARγ to target Ucp1 transcription, thereby improving obesity and its related disorders, such as glucose utilization, insulin sensitivity and liver steatosis." (PMID 38332049, 2024). "Together, these animal and human studies demonstrate that obesity disrupts brain endothelial insulin transport, reducing insulin delivery to the CNS." (PMID 38678254, 2024). "Irisin and FGF21 act as adipokines beiging adipocytes that attenuate diet-induced obesity by stimulating thermogenesis and increase insulin sensitivity." (PMID 39267855, 2024). "Alterations in insulin transport have also been observed in obesity, which can profoundly impact neuronal function." (PMID 38678254, 2024). "FTO is a major genetic link between breast cancer, obesity, and diabetes PPARG regulates adipocyte differentiation, lipid storage, and glucose metabolism, affecting insulin sensitivity and linking it to obesity, metabolic syndrome, and type 2 diabetes." (PMID 39769194, 2024). "Obesity can cause elevated levels of FFA in follicular fluid, insulin can inhibit the release of FFA from adipose tissue, and the presence of IR can attenuate this effect, leading to the accumulation of FFA in the blood." (PMID 38348417, 2024). "In general, the personalized E-DES models displayed good agreement with the data both when calibrated on plasma glucose as well as CGM glucose in a wide range of glucose and insulin responses after an OGTT in individuals with overweight or obesity." (PMID 38580749, 2024). "Nevertheless, these higher levels of serum insulin are decreased when we administered TAC on top of obesity." (PMID 38745946, 2024). "Obesity results in reprogramming of cardiac metabolism that includes impaired glucose uptake and oxidation for a given insulin concentration." (PMID 38225272, 2024). "Further studies in homogenous groups of patients with varying degrees of obesity would be necessary to understand the effect of FTO genetic variations on systemic insulin resistance and the specific effects on bone." (PMID 39336743, 2024). "T2DM and obesity are states of hyperinsulinemia, and insulin is known to directly activate IGF1-R on epidermal cells and increase IGF1 levels in the blood, which is the proposed mechanism of action of AN in hyperinsulinemic states." (PMID 39165464, 2024). "Subgroup analyses indicated a notable reduction in serum levels of insulin in the SIL-treated group compared to controls in studies among participants with overweight or obesity, in short-term or long-term supplementation with low or high doses of SIL." (PMID 38671838, 2024). "Firstly, the reclassification is neatly tied in with CMD polygenicity, and methylation closely agrees with genes involved in insulin signalling, obesity and aging." (PMID 39511564, 2024). "On the other hand numerous data show that dietary supplementation with RJ improves oxidative stress, inflammation, lipid metabolism, and insulin sensitivity, suggesting its potential use in the prevention of obesity-related metabolic disorders." (PMID 38892209, 2024). "This adaptation significantly improves local and systemic insulin sensitivity, and energy expenditure, offering a potential avenue to combat obesity-related metabolic dysfunction." (PMID 38555350, 2024).
Obesity (continued). "These insights not only explain the naturally occurring right-shift of the insulin response curve but also suggest the therapeutic potential of targeting the insulin signaling pathway to treat obesity and type 2 diabetes (T2D)." (PMID 39617270, 2024). "All articles describing the mechanisms responsible for the development of infertility and PCOS, with a focus on the role of obesity, insulin sensitivity and treatment with metformin and GLP-1s were considered for this review." (PMID 38540265, 2024). "improving glucose tolerance and stimulating insulin secretion, and preventing obesity by activating the AMPK signalling pathways." (PMID 38090734, 2024). "Treatment with E2 has been shown to protect against obesity and alterations in glucose-insulin homeostasis in male mice fed high-fat diets, and to regulate leptin sensitivity to modulate feeding." (PMID 38883397, 2024). "Insulin has been shown to increase DHT levels through activation of 5-α-reductase activity in patients with obesity." (PMID 39135763, 2024). "Klotho-overexpressing mice exhibit increased insulin sensitivity and resistance to diet-induced obesity." (PMID 38501099, 2024). "Individuals with overweight or obesity have been reported to show an increased number of activated macrophages, which produce inflammatory mediators that can inhibit the action of insulin." (PMID 38347961, 2024). "However, it might also be that early-life insulin exposure is associated with young adulthood venular tortuosity, whereas in mid-adulthood the association might be blunted by related cardiometabolic risk factors such as obesity and inflammation." (PMID 39661465, 2024). "Several studies have indicated that, while circulating FGF21 levels are elevated, its signal transduction and actions are impaired in the skeletal muscles of patients with T2DM and insulin-resistant human skeletal muscle myotubes with diet-induced obesity." (PMID 39640300, 2024). "IR, assessed by HOMA-IR, is fundamental for the development and worsening of metabolic changes in obesity, and preserved insulin sensitivity is a characteristic of MHO individuals." (PMID 39330509, 2024). "As anticipated, myotubes from donors with severe obesity were initially insulin resistant; however, despite this impairment, there was a main treatment effect for resveratrol indicating enhanced insulin action." (PMID 38324260, 2024). "In women, obesity can affect fertility and reproduction in different ways, including interference with spontaneous ovulation, steroid metabolism and secretion, and insulin activity." (PMID 39742100, 2024). "In conclusion, the data generated from the current study suggested that the two extracts under investigation are considered potential candidates for controlling insulin levels and managing obesity." (PMID 38931172, 2024). "In this review, we highlight the key organs involved in maintaining BCAA homeostasis and discuss how obesity and insulin resistance disrupt the intricate interplay among these organs, thus affecting BCAA balance." (PMID 39007094, 2024). "The mechanism of HTG in obesity involves insulin resistance, which results in an elevated flow of free fatty acids (FFA) from belly fat to the liver." (PMID 39185300, 2024). "Obesity also results in increased levels of insulin and leptin and upregulates levels of endogenous hormones, including insulin and sex steroids." (PMID 39272806, 2024). "We also draw attention to the calcium–magnesium interrelationship, crucial both in obesity and pediatric MetS, as well as in insulin homeostasis (correlated inversely proportionally with the value of magnesium)." (PMID 39723164, 2024). "Multiple clinical trials have aimed at increasing SCFA levels in participants with impaired insulin sensitivity, preexisting overweight/obesity, or multiple gastrointestinal abnormalities." (PMID 37290429, 2024).